CRP (C-reactive protein)
Diseases named in the same sentence as CRP in open-access papers (continued):
Sharing a sentence is not in itself a finding about the gene and the disease.
depression (continued). "For example, elevated concentration of C-reactive protein (CRP; >3 mg/L) has been detected in 21%–34% of patients with depression, along with increased concentrations of IL-6 and other inflammatory cytokines in blood and in cerebrospinal fluid (51, –, 54)." (PMID 38421192, 2024). "Further, we also explored the potential mediating role of systemic inflammation, measured by C-reactive protein (CRP) levels, in the chronotype-depression link." (PMID 39562745, 2024). "IL-6 and CRP are the two most commonly increased inflammatory factors, and the nerve growth factor (NGF) is the most commonly decreased factor in depression and schizophrenia." (PMID 39058106, 2024). "A meta-analysis comprising individuals both with and without cardiovascular disease demonstrated a correlation between elevated levels of C-reactive protein (CRP), IL-1, and IL-6, and depression." (PMID 38809848, 2024). "Since then, many studies have demonstrated increased levels of acute-phase proteins and pro-inflammatory cytokines such as C-reactive protein (CRP), IL-1, IL-1β, IL-6 and TNF-α in depression." (PMID 38575920, 2024). "Our findings further indicate that the impacts of both depression and urate levels on LTL are partly exerted through CRP, highlighting inflammation’s role as a mediating factor of LTL shortening." (PMID 38760657, 2024). "Previous research has demonstrated that major depressive disorder patients are in a proinflammatory state, with elevated levels of innate immune plasma mediators such as IL-6, TNF-a, and C-reactive protein." (PMID 37924045, 2023). "We find the proportion of subjects with RA to be significantly different (P < 0.05) for all situations, except when depression and HTG were considered at the low level of CRP." (PMID 38455932, 2023). "Activity was assessed according to the DAS28(ESR), DAS28(CRP), SDAI, CDAI; functional ability to HAQ; quality of life to the EQ-5D; disease activity according to the patient’s RAPID-3 index; the level of depression and anxiety to the HADS scale." (PMID 37833604, 2023). "Studies have reported that IL-6, TNF-α, CRP, YKL-40, IL-17, IL-1β, CCL2, IL-2, and IL‐8 are related to worse cognitive function or cognitive deterioration, while CRP, TNF-α, sIL-2R and CCL2 reflect severe symptoms of depression and anxiety." (PMID 36739284, 2023). "For instance, C-reactive protein (CRP) and cytokines, including interleukin-1, interleukin-2, interleukin 6, interleukin-1β, and interferon-γ, were released in response to depression." (PMID 37111321, 2023). "However, CRP alone may not be sufficient to identify the immune-related biological and molecular modifications associated with depression." (PMID 37264010, 2023). "The patients showed a significant increase in the levels of inflammatory markers IL-1β (p < 0.001), TNF-α (p < 0.001), and CRP (p < 0.001), despite improvement in PTSD (p < 0.001) and depression (p < 0.001) symptoms from baseline through one year follow-up." (PMID 37081449, 2023). "Participants were evaluated for depressive symptoms using the Beck Depression Inventory-II (BDI-II) and had blood work quantifying IL-6 and CRP at baseline and during follow-up visits." (PMID 38299049, 2023). "Multiple meta-analyses showed that there were differences in pro-inflammatory cytokines between patients with severe depression and the control group, including IL-6, TNF-α, IL-1β, and CRP." (PMID 36846218, 2023). "Depressive symptoms were measured using the 10-item Center for Epidemiologic Studies Depression Scale (CESD-10), and the C-reactive protein (CRP) level was used to measure individual inflammation levels." (PMID 36860788, 2023). "Mental disorders, especially depression, partially share some pathophysiological mechanisms of IBD, including oxidative stress, increased proinflammatory cytokines and C-reactive protein (CRP), dysbiosis, and gut permeability." (PMID 37109640, 2023).
depression (continued). "In the serum of patients with cardiovascular disease and depression, the levels of IL6 and CRP are higher than those of normal people, and more critically, IL6 and CRP can link the brain and heart through blood circulation." (PMID 38084332, 2023). "Understanding the inflammatory basis of MDD can aid in the identification of specific biomarkers of inflammation such as IL-6 and CRP to provide a more personalized treatment approach and informed therapeutic strategy in patients with Treatment Resistant Depression (TRD)." (PMID 38299049, 2023). "Hence, the use of CRP may not precisely capture the causal pathway by which systemic inflammation affects depression-related brain functioning." (PMID 36462595, 2023). "Cytokines, which mediate the innate immune response, including IL-1, tumor necrosis factor (TNF)-alpha, C-reactive protein (CRP), and IL-6, from peripheral blood are considered the most reliable biomarkers of inflammation in patients with depression." (PMID 37065487, 2023). "Several meta-analyses have found positive correlations between blood levels of both CRP and IL6 with depression." (PMID 38299049, 2023). "In within-person temporal networks, higher CRP and HDL predicted all three depression components (d = 0.131–2.112)." (PMID 35924730, 2023). "According to extensive reports, high levels of pro-inflammatory and inflammatory markers impacted the inflammatory response to depression, namely, interleukin-1(IL-1), IL-18, IL-6, tumor necrosis factor-α (TNF-α), IFN-γ, and C-reactive protein (CRP)." (PMID 37090985, 2023). "There were 31 RA patients, 16 with active disease activity and 15 in remission state; they were assessed using the Hospital Anxiety and Depression Scale and for RA disease activity using Disease Activity Score of 28 joints (DAS28) – CRP (C-reactive protein)." (PMID 37916198, 2023). "Patients in manic episodes showed higher levels of testosterone, estradiol, progesterone, and CRP (P < 0.001) and lower levels of ACTH (P < 0.001) than those in depressive episodes." (PMID 37340368, 2023). "Studies have shown that depression is related to the expression of a variety of molecules, including IL-6, IL-2, IL-1β, TNF-α, and C-reactive protein (CRP)." (PMID 36010610, 2022). "Brain derived neurotrophic factors (BDNF); Chamomile; C-reactive protein (CRP); Depression; Patient health questionnaires 9 (PHQ-9); Saffron; Tryptophan (TRP)." (PMID 36217471, 2022). "Clinical trials suggest that when the inflammation level is high initially (C-reactive protein >5 mg/dL), combined use of cytokine antagonists (e.g., TNF antagonist infliximab) and antidepressant therapy can improve the course of depression." (PMID 36619667, 2022). "Enormous studies have manifested increased levels of proinflammatory cytokines such as CRP, IL-1β, IL-6, and TNF-α in elderly patients with depression (and the patients underwent surgery)." (PMID 35356751, 2022). "Among inflammatory markers, elevated levels of C-reactive protein, IL-6, and TNF are the most reliable markers of depression." (PMID 36619667, 2022). "No other difference in ESSPRI, ESSDAI, SF-36, the HADS anxiety subscore, the HADS depression subscore, Schirmer test results, unstimulated saliva flow, ESR, the CRP level, or the IgA or IgM concentration between the 2 groups was obtained in any other week." (PMID 35602489, 2022). "In similar studies, patients with depression were found to have elevated levels of proinflammatory cytokines, including tumor necrosis factor-α (TNF-α), interleukin 1β (IL-1β), IL-6, and C-reactive protein (CRP)." (PMID 35054853, 2022). "Levels of CRP, a peripheral inflammatory indicator, correlated positively with the PHQ-9 total score of patients who presented symptoms of depression." (PMID 36117646, 2022). "The biomarkers assessed in the studies involving depression include IL-6 (n = 5), IL-10 (n = 4), TNF-α (n = 4), IL-1β (n = 2), CRP (n = 2), and IL-7 (n = 1)." (PMID 35053845, 2022).
depression (continued). "Data consistently demonstrates that a subset of patients with depression show elevated levels of inflammatory biomarkers including Interleukin-6 (IL-6), Interleukin-1Beta (IL-1β), Tumour Necrosis Factor-alpha (TNF- α) and CRP." (PMID 35146459, 2022). "Patients with depression often have elevated TNF-α, IL-1, IL-1β, IL-2, IL-6, IL-8, IL-17, IL-21, IL-23, C-reactive protein, and TGF-β." (PMID 35054853, 2022). "In the patients who scored higher on the Hamilton Depression Rating Scale (HAM-D), there was a significant correlation between Hamilton Anxiety Rating Scale (HAM-A) and HAM-D scores, as well as C-reactive protein (CRP) levels and WBC counts." (PMID 35371847, 2022). "However, we do not find evidence for a potentially causal role for CRP on depression or for potentially mediating role for CRP on the association between smoking and depression, though we did find evidence for a potentially mediating role for IL-6 activity on this association." (PMID 36057695, 2022). "A meta-analysis of the mean differences and variability in 5166 patients and 5083 controls showed that the levels of CRP, IL-3, IL-6, IL-12, IL-18, sIL-2R, and TNF-α were significantly higher in patients with depression." (PMID 35409300, 2022). "Compared with the non-depression group, patients with depressive symptoms had higher levels of inflammatory cytokines, including IL-1, IL-6, TNF-α, and CRP." (PMID 35757220, 2022). "We performed ROC analysis to distinguish the depression of patients with different clinical characteristics according to the IL-6, TNF-α, and CRP values." (PMID 35757220, 2022). "Serum IL-6, IL-17, and CRP were measured before and after selective serotonin reuptake inhibitor (SSRI) therapy, as well as Hamilton rating scale for depression (HAMD) and life event scale (LES) scores." (PMID 35615531, 2022). "In a study conducted on a cohort of obese women, increased levels of various pro-inflammatory markers, including IL-6, C-reactive protein (CRP), and adipokines, were correlated directly with the symptoms of anxiety and depression." (PMID 35456757, 2022). "Outcomes measures included pain, physical function, disease activity, erythrocyte sedimentation rate (ESR), C-reactive protein (CRP), anxiety, depression, Arthritis Self-Efficacy (pain, other symptoms, total), and General health." (PMID 35370836, 2022). "Depression-like behaviors are related to increased peripheral blood levels of IL-1β, IL-6, TNF, and CRP, the most reliable biomarkers of inflammation." (PMID 36278007, 2022). "Depression was assessed using the revised Beck Depression Inventory (BDI-II) and the heritability of CRP levels was evaluated through Structural Equation Modelling." (PMID 35163538, 2022). "Resolving the extent to which the relationship between CRP and psychiatric symptoms is moderated by psychosocial and health factors is important not only because it may inform our understanding of the pathophysiology of depression, but because it may provide opportunities for intervention." (PMID 35821205, 2022). "The Young Manic Rating Scale (YMRS), Self-Rating Depression Scale (SDS), and Interleukin-6 (IL-6), Tumor necrosis factor-α (TNF-α) and C-reactive protein (CRP) levels will also be measured." (PMID 36458119, 2022). "Low high-density lipoprotein cholesterol levels are associated with increasing triglyceride levels (p < 0.001), increasing high-sensitive C-reactive protein (hs-CRP) levels (p = 0.021), younger age (p < 0.001), male sex (p < 0.001), and depression (p = 0.045)." (PMID 35911274, 2022). "In a recent publication, less depression in EGFR mutant NSCLC patients was documented, probably mediated by lower CRP‐related inflammation." (PMID 34877613, 2022). "A correlation was also observed between depression and CRP, IL-6, and IL-1ra in CTQ+ participants; perceived stress also links up with CRP and IL-6." (PMID 36231913, 2022).
depression (continued). "It has been reported that pro-inflammatory markers, including IL-1β, IL-6, TNF-α, and C-Reactive Protein (CRP), are significantly higher in the elderly with depression and AD." (PMID 35164003, 2022). "A cross-sectional study assessed 6005 Finns aged >30 years for depression, using BDI and CIDI, and for CRP levels." (PMID 35163538, 2022). "Logistic regression was used to analyze the_association of DII and C-reactive protein (CRP) quartile scores with depressive symptoms in total participants and participants with different dietary fiber intakes and to further explore whether dietary fiber influences depression through inflammation." (PMID 36713916, 2022). "Clinical evidence showed that inflammatory mediators were elevated in patients with depressive disorder, such as HMGB1, IL‐1β, TNF‐α, CRP, IL‐6, and so on." (PMID 35089644, 2022). "Based on two markers, CRP and WBC, we found inflammation at baseline predictive of new cases of depression at follow-up 5 years later." (PMID 33500534, 2021). "According to the classified stage of depression, current disease activity (DAS28-CRP: 28-Joint RA Disease Activity Score-C-reactive protein) and the health assessment questionnaire disability Index (HAQ-DI) were significantly increased." (PMID 34351967, 2021). "The harsh conditions incurred during cancer treatment (chemotherapy and radiation) has been correlated with the increase of inflammatory mediators such as C-reactive protein (CRP) and interleukin (IL)-6, which can promote depression." (PMID 34371931, 2021). "Depression has sustained a series of inflammatory state, and promoted the increase of inflammatory markers, such as tumor necrosis factor-α (TNF-α), C-reactive protein (CRP) and interleukin 6 (IL-6)." (PMID 34421539, 2021). "CRP, sTNFR1, IL-6 and its soluble receptor and monocyte chemoattractant protein-1 (MCP-1) were found to be higher in BD in comparison with unipolar depression." (PMID 33946871, 2021). "However, on average, meta-analytic reviews have argued for the presence of a CM-elevated CRP in adulthood association that is independent of age, gender, and body mass index, and that these two factors are also significantly associated with depression." (PMID 34867491, 2021). "Meta-analyses of cross-sectional studies confirm elevated concentrations of circulating inflammatory cytokines and acute phase proteins, like interleukin-6 (IL-6) and C-reactive protein (CRP), in patients with depression as compared to controls." (PMID 34729541, 2021). "In conjunction with measures of pregnancy-specific anxiety and depression, serum biomarkers (IL-2, IL-6, IL-10, IL1-B, TNF-α, CRH, CRP, and cortisol) were analyzed for each trimester throughout pregnancy." (PMID 34360332, 2021). "Meta-analyses reported strong evidence of significantly increased levels of c-reactive protein (CRP), IL-1, IL-6, TNF-α and soluble IL-2 receptor in the serum of major depressive disorder (MDD) patients." (PMID 34440101, 2021). "Third, observational data indicate that peripheral inflammatory biomarkers, including interleukin-6 (IL-6), and C-reactive protein (CRP), are consistently elevated in depression." (PMID 34589778, 2021). "This association is especially seen in atypical depression, where subjects show increased appetite along with symptoms of depression, which then correlate with elevated serum (TNF-α) and C-reactive protein (CRP) levels." (PMID 33557031, 2021). "Biologically, elevated depression might have this adverse effect on EF across prolonged durations via chronic wear-and-tear of the hypothalamic–pituitary–adrenal axis function, such as buildup of glucocorticoids and proinflammatory cytokines (e.g., C-reactive protein)." (PMID 34134796, 2021). "Following CRP stratification, significantly higher TSPO binding was observed in low-CRP depression compared with controls (d = 0.53; t54 = 1.96, p = .03)." (PMID 33515765, 2021).
depression (continued). "Mechanistically, patients with depression as well as individuals with post-traumatic stress disorder have increased levels of systemic inflammatory markers, such as IL-6 and C-reactive protein (CRP), compared to healthy controls, which could trigger inflammatory arthritis in predisposed subjects." (PMID 34830268, 2021). "High levels of PTSD and depression symptoms may lead to chronic dysregulation of the hypothalamic–pituitary–adrenal axis and increased levels of systemic inflammatory markers, including interleukin-6 and C-reactive protein, which may be elevated prior to RA onset." (PMID 34071429, 2021). "A variety of evidence implicates IL-6 in the pathogenesis of depression, and a phase 2 trial of sirukumab for patients with MDD and CRP >3 mg/L has recently completed (clinicaltrials.gov ID: NCT02473289)." (PMID 31427751, 2020). "We found increases in the mean levels of CRP, IL-3, IL-6, IL-12, IL-18, sIL-2R and TNF α in patients with depression." (PMID 32113908, 2020). "Among inflammatory markers, IL-6, C-reactive protein (CRP), TNF-α and soluble interleukin-2 receptor (sIL-2R) appear to have the greatest potential to serve as markers for depression." (PMID 33255237, 2020). "Patients with depression have increased pro-inflammatory cytokines in blood, such as IL-1β, IL-6, TNF-α, and other acute phase proteins, C-reactive protein (CRP)." (PMID 32513185, 2020). "PD patients have elevated levels of CRP, CCL-2, IL-6, and of TNF-alpha, correlating partially with fatigue, depression and anxiety, and with cognitive deficits." (PMID 32072462, 2020). "CRP is produced by hepatocytes under the regulatory control of IL-6 and other inflammatory cytokines, and these pro-inflammatory cytokines cause sickness behaviors, such as weakness, depression, exaggerated pain (hyperalgesia or allodynia), and lack of appetite." (PMID 33054839, 2020). "The entire population showed low systemic inflammation (median CRP = 3.0 mg/L, IQR: 1.3–6.0) and low rates of fibromyalgia (6%) and depression (8%)." (PMID 32560321, 2020). "Our findings of increased inflammation (IL-6, CRP, MCP4, TARC) also align with previous research finding increased pro-inflammatory cytokines in treatment-resistant versus responsive patients with depression." (PMID 33276697, 2020). "Interestingly, in this present, much larger study, patients with depression, diagnosed at the hospital, had significantly higher level of CRP than dementia-free patients, thus supporting the hypothesis of the role of immunological mechanisms in development of depressive symptoms." (PMID 33213019, 2020). "Previous studies found that pro-inflammatory cytokines, including tumor necrosis factor-α (TNF-α) and interleukin (IL)-6, IL-1β, and C-reactive protein (CRP), are markedly increased in the blood and CSF of patients with depression." (PMID 32922295, 2020). "Compared with these two groups, higher levels of SOD, CAT, and GSH-Px but lower levels of CRP, IL-6 and TNF-α were observed in the depression group." (PMID 32973539, 2020). "Meta-analyses have shown that inflammation is connected with depression, i.e., the elevated C-reactive protein, interleukin 6 (IL-6), and tumor necrosis factor alpha (TNF-α) in major depressive disorder." (PMID 32581890, 2020). "Decreasing HDL-cholesterol levels were associated with increasing triglyceride levels (p < 0.001), increasing high-sensitive C-reactive protein (hs-CRP) levels (p = 0.021), younger age (p < 0.001), male sex (p < 0.001), and depression (p = 0.045)." (PMID 30885233, 2019). "Increases in biomarker levels were correlated with reduction in depression severity for TNF-α, IL-6 IL-10 and CRP." (PMID 31375659, 2019). "Standard measures of depression, anxiety, perceived stress, health related quality of life (HRQOL), blood pressure, biomarkers (lipids, HbA1c, CRP) and 24-hour Holter monitoring were obtained at baseline, 3- and 9-months post-randomization." (PMID 31804580, 2019).